BDNF (brain derived neurotrophic factor)
Diseases named in the same sentence as BDNF in open-access papers (continued):
Sharing a sentence is not in itself a finding about the gene and the disease.
neurological disorders (continued). "This review and meta-analysis suggest that a program of aerobic exercise can increase levels of BDNF in people with a neurological disorder when compared to usual care or nil therapy." (PMID 29057125, 2017). "Low BDNF levels have been shown to decrease neuronal survival, growth, differentiation and plasticity, and were reported in a wide array of neurological diseases and conditions." (PMID 29179434, 2017). "In contrast, the goal of the present review is to give a more generalized overview of the involvement of BDNF in the pathology of the most prevalent psychiatric and neurological disorders, compiling what is known from human, animal, and in vitro studies." (PMID 35098038, 2017). "The neuroprotective and pro-neurogenesic effects of BDNF have been widely explored against a myriad of neurological disorders in which reversal of the reduced BDNF level in the affected brain regions have produced encouraging results." (PMID 28335495, 2017). "In this sense, abnormal BDNF signaling has been proposed to have a crucial role in the course and development of numerous psychiatric and neurological disorders." (PMID 35098038, 2017). "The present review gives an overview of the involvement of BDNF in the pathology of psychiatric and neurological disorders, compiling what is known from human and animal studies." (PMID 35098038, 2017). "For this reason, interference with BDNF signaling has emerged as a promising strategy for potential treatments in psychiatric and neurological disorders." (PMID 28280960, 2017). "Abnormal BDNF signaling has been proposed to have a crucial role in the course and development of numerous psychiatric and neurological disorders." (PMID 35098038, 2017). "BDNF is a molecule that is also involved in promoting memory and neurogenesis and is reduced in the brain with age and in AD, as well as in other neurological disorders." (PMID 28709449, 2017). "Given all these similarities, we believe that drug discovery effort aimed at enhancing both BDNF and progranulin levels is of great interest for the prevention and cure of psychiatric and neurological disorders." (PMID 26869919, 2016). "A further study on the role of this neurotrophin in different neurological diseases observed lower levels of BDNF protein in serum of FTLD AD, LBD and vascular dementia patients, whereas the protein was increased in PD patients." (PMID 26869919, 2016). "Decreases of BDNF and its receptor TrkB levels and activity are accompanied by and are believed to lead to several pathologies, particularly nervous system diseases like neurodegenerative, psychiatric and cognitive diseases." (PMID 27386199, 2015). "BDNF was shown to exert neuroprotective effects in several experimental models of neurological diseases." (PMID 26223433, 2015). "HDAC inhibitors are one class of drugs that have been shown to mediate their effect on memory and synaptic plasticity in models of nervous system disorders through increase in BDNF expression." (PMID 24943717, 2014). "Due to BDNF involvement in nervous system disorders, it has been of great interest to use it as a therapeutic." (PMID 24943717, 2014). "Some of these genes and pathways (DARPP-32 and BDNF) have already been well characterized in other neurological diseases." (PMID 24804781, 2014). "Brain derived neurotrophic factor is of particular therapeutic interest because its expression level is altered in many neurological disorders." (PMID 23320097, 2013). "Neuroprotective effects of systemic BDNF have been described in several models of neurological disorders." (PMID 23700454, 2013). "Collectively, findings reviewed in this paper provide a rationale for targeting BDNF signaling for novel therapeutic interventions in a range of metabolic and neurological disorders." (PMID 22548651, 2012).
neurological disorders (continued). "Discussion will then shift towards the value of these methods in studying the role of BDNF in the following neurological disorders: (i) Val66met, a subclinical condition defined by a common single nucleotide polymorphism in (SNP) in the pro region of BDNF." (PMID 22720171, 2012). "Currently, this knowledge of BDNF function is being translated into improvement strategies for several debilitating neurological disorders in which BDNF abnormalities play a prominent role." (PMID 22720171, 2012). "Recent investigations revealed a relationship between BDNF and various neurological disorders such as Parkinson’s disease, Alzheimer’s disease, depression, and anxiety-related personal trait." (PMID 22606023, 2012). "Out of 84, 24 BDNF-correlated genes are related to cancer and 14 are involved in neurological disorders." (PMID 19737418, 2009). "Overall, with adding in exercise-induced BDNF, including pharmacological and task-specific approaches, creates a highly potent package of neuromodulatory strategies to promote neuroplasticity and neuroplastic recovery across neurological disease contexts." (PMID 40362507, 2025). "Here, we show recent evidence in regulation of the BDNF/TrkB system by small molecules using in vivo and in vitro disease models, to take critical insights for developing the potential therapeutic approach to mental and neurological disorders." (PMID 40005159, 2025). "Our study offers new insights into the role of BDNF in regulating the levels of circulating inflammatory proteins and paves the way for future research and the development of therapeutic strategies in inflammation-related neurological diseases." (PMID 40133606, 2025). "The balance of BDNF and these factors may play a crucial role in inflammation-related neurological diseases." (PMID 40133606, 2025). "Additionally, the interaction between BDNF and other signaling pathways, such as Wnt/β-catenin, suggests a promising avenue for the development of treatment strategies in neurological diseases." (PMID 40149774, 2025). "BDNF has well-documented roles beyond the nervous system, including modulation of immune cell function, cell death mechanisms, and protective effects against ferroptosis in neurological disease models." (PMID 40738187, 2025). "This suggests that class II HDACs directly repress BDNF promoter IV activity, and selective inhibition of these enzymes may offer therapeutic potential for neurological disorders by enhancing BDNF-mediated signaling." (PMID 40867911, 2025). "Further research regarding these stages could further explain the aberrant secretion of BDNF observed in neurological disorders." (PMID 41254423, 2025). "Physical activity, particularly resistance training, significantly increases both muscle expression and circulating levels of BDNF, with beneficial effects observed in young individuals as well as in older adults and patients with metabolic or neurological disorders." (PMID 41441428, 2025). "Recently, it has also been shown that several antidepressants (such as fluoxetine or imipramine) work through directly binding to TrkB and promoting BDNF signaling, further stressing the importance of pursuing TrkB as a valid target to treat various neurological disorders." (PMID 39274839, 2024). "The fact that BDNF can increase neurogenesis and neuroplasticity suggests that it may play a considerable role in various neurological disorders." (PMID 37287291, 2024). "Understanding this relationship opens up new avenues for studying how BDNF stored in platelets may impact on neurological disorders and potential treatment strategies." (PMID 39568824, 2024). "We hypothesize that a standardized OA, CH, and BA-containing supplements based on Oroxylum indicum could be useful in treating such neurological disorder conditions by increasing the production of BDNF." (PMID 38931243, 2024).
neurological disorders (continued). "Moreover, CSF and serum levels of BDNF are reduced in RRMS patients during relapse compared to patients with other neurological diseases due to an abnormal immune response and the synthesis of BDNF." (PMID 39654365, 2024). "Furthermore, many drugs influence the levels of BDNF in the serum and its expression in various neurological diseases." (PMID 38752280, 2024). "By expressing and releasing BDNF in astrocytes to support neurons, the BDNF mRNA effectively enhanced memory function in AD model mice, thus highlighting the potential of mRNA therapy in the treatment of neurological diseases." (PMID 39543114, 2024). "Moreover, various medications affect the expression and BDNF serum levels in different neurological disorders." (PMID 38006577, 2024). "Simultaneously, curcumin, which plays a positive role in treating various neurological diseases, can exert therapeutic effects on neuropathic pain by downregulating the expression of the BDNF and Cox‐2 genes, in a manner mediated by p300/CREB‐binding protein histone acetyltransferase activity." (PMID 39648800, 2024). "Future studies might improve the BDNF analysing methods in laboratories, thus making it a more reliable biomarker for disease severity and a potential therapeutic target for complex neurological disorders." (PMID 38539631, 2024). "Increasing BDNF by different modalities including cognitive stimulation, diet restriction, in vivo and exvivo delivery of BDNF, BDNF mimetics and direct administration of BDNF may improve certain neurological disorders." (PMID 38006577, 2024). "Further research is essential to understand the precise mechanisms by which platelet-derived BDNF might impact neurological disease." (PMID 39568824, 2024). "Similarly, increases in BDNF levels have been documented in patients with neurological disorders, including stroke, following aerobic exercise interventions." (PMID 39935805, 2024). "Changes in gene expression via BDNF may offer a novel therapeutic approach for treating neurodegenerative and neurological diseases." (PMID 39595072, 2024). "Moreover, there are reports suggesting that BCL11B serves as a novel regulatory factor in the brain-derived neurotrophic factor (BDNF) signaling pathway 30, which is disrupted in many neurological disorders." (PMID 39239553, 2024). "However, the regulation of BDNF by acupuncture is not limited to these diseases, and scholars will explore the effects of acupuncture on BDNF in more neurological disorders in the future." (PMID 37780709, 2023). "BDNF delivery has been shown to be very useful in animal models of neurological disorders." (PMID 36986535, 2023). "Further investigation will address whether, as for the mouse gene, multiple enhancers regulate the human BDNF gene, determining distinct spatiotemporal expression patterns that may be perturbed in neurological disorders." (PMID 36582820, 2023). "This review will discuss the modulation of BDNF by acupuncture in several neurological diseases." (PMID 37780709, 2023). "Some studies found that expression of BDNF is decreased in ATXN‐mutant mice and delivery of BDNF could ameliorate ATXN‐mutation‐related neurological diseases." (PMID 37072935, 2023). "The relation between BDNF alteration and neurological disorders suggest that BDNF could be consider a valid biomarker and therapeutic factor." (PMID 38025444, 2023). "Because of this, modulating BDNF levels could be a potential therapeutic tool for neurological disorders." (PMID 37780709, 2023). "Brain-derived neurotrophic factor (BDNF), a member of the neurotrophin family, is associated with the regulation of neuronal reorganization and is involved in the pathogenesis of many neurological diseases." (PMID 37735708, 2023). "Notably, we can find that acupuncture’s modulation of BDNF levels in other neurological diseases is upregulated, and only for neuropathic pain is BDNF levels downregulated." (PMID 37780709, 2023).
neurological disorders (continued). "Dysregulated expression of BDNF has been reported for a number of neurological disorders." (PMID 36922901, 2023). "BDNF plays important roles in promoting neurite development, neuronal survival and long-term maintenance of synapse integrity and dendrite maintenance, rendering BDNF an appropriate therapeutic target for neurological disease." (PMID 36922901, 2023). "In addition, BYHWD was shown to be able to alleviate neurologic disorders after injury by activating the Wnt/β-catenin signaling pathway and elevating the expression levels of BDNF and NGF." (PMID 36906602, 2023). "Indeed, vildagliptin had been reported to restore cognitive function in neurological disease models by activating BDNF signalling cascades." (PMID 38082288, 2023). "NTs have been widely used as biomarkers and especially BDNF in neurological diseases." (PMID 36263167, 2022). "Thus, the possibility of promoting BDNF/TrkB signaling has become relevant as a potential therapeutic intervention for neurological disorders." (PMID 35845610, 2022). "Although they performed the meta-analysis considering all of the neurologic disorders, their results align with the current study and indicate that exercise might contribute to increased BDNF concentrations." (PMID 35239684, 2022). "The disruptions in BDNF production that result in signaling-cascade failure may be responsible for a range of neurological disorders." (PMID 35743271, 2022). "Cortical Nurr1 and BDNF are reduced in neurological disorders exhibiting impairment." (PMID 35743300, 2022). "In addition, BDNF serves as a crucial molecular target for the development of drugs to treat neurological diseases." (PMID 35743271, 2022). "Thus, enhancing the BDNF signaling has a beneficial effect on the overall metabolism, particularly in preventing or treating metabolic and neurological disorders." (PMID 36101441, 2022). "BDNF induction could serve as one of the therapeutic strategies against neurological disorders; thus, compounds based on BDNF inducer scaffold might provide a plausible multi-target agent against AD." (PMID 35626478, 2022). "Present only in humans, the “Val66Met” polymorphism of the BDNF gene (BDNF) is suggested to have a negative influence on the etiology of neurological diseases." (PMID 34025349, 2021). "Several previous studies support the idea that the transcriptional machinery involved in BDNF expression could be altered in the brains of patients with these neurological diseases." (PMID 34977362, 2021). "These and the present findings raise the interesting possibility that the right dosage of EE might ameliorate BDNF-dependent deficits in other neuropsychiatric and neurological disorders." (PMID 33888685, 2021). "Brain-derived neurotrophic factor (BDNF) is a neuroprotective factor that may have various effects on the pathogenesis of some neurologic disorders." (PMID 32509339, 2020). "A number of reports show lower BDNF levels in brains with neurological diseases." (PMID 32894176, 2020). "Changes in brain BDNF have been reported for probiotics such as Bifidobacterium in rodent experiments and have a beneficial effect on genes and inflammation pathways involved in neurological disorders." (PMID 32623402, 2020). "Therefore, this method will facilitate further understanding of the relationship between alterations in BDNF levels in the brain and pathophysiology of neurological diseases, assuming that disease model mice can be generated using Bdnf-Luc mice." (PMID 32894176, 2020). "The potential use of caposomes as a protein delivery carrier has been demonstrated by several studies; special mention must be made to studies in which caposomes were employed to encapsulate the brain-derived neurotrophic factor (BDNF) for the treatment of neurological disorders." (PMID 32722622, 2020).
neurological disorders (continued). "More importantly, C. asiatica and its extracts improved neurological diseases by reducing inflammatory factors, balancing oxidative stress, repairing abnormal expression of mitochondrial-related proteins, and improving the content of BDNF." (PMID 33013406, 2020). "Together, these reports strongly suggest that identifying inducers of BDNF expression, or activators of TrkB, may contribute to identifying candidate agents and improving symptoms of neurological diseases." (PMID 31413298, 2019). "Together these results suggest that FTO may be a possible new target to find novel approaches for the treatment of neurological diseases via regulating BDNF processing." (PMID 30730976, 2019). "Acupuncture treats nervous system diseases by increasing the brain-derived neurotrophic factor level and involves multiple signal pathways, including p38 MAPKs, Raf/MAPK/ERK 1/2, TLR4/ERK, PI3K/AKT, AC/cAMP/PKA, ASK1-JNK/p38, and downstream CREB, JNK, m-TOR, NF-κB, and Bcl-2/Bax balance." (PMID 31379957, 2019). "Due to the contrasting effect of proBDNF and mBDNF on the function of neurons, the regulation of BDNF processing and the involvement in signaling pathways has become the focus of research in order to find possible new approaches for the treatment of neurological diseases." (PMID 30730976, 2019). "Increased expression of BDNF can reduce neuronal synaptic damage in nervous system diseases." (PMID 30050927, 2018). "BDNF/CREB pathway is a pharmacological target of many neurological disorder therapies." (PMID 29465826, 2018). "Thus, understanding the epigenetic regulation at the BDNF promoters will shed light on future therapies for neurological disorders." (PMID 28272318, 2017). "However, the change of histone modifications that affect BDNF expression in neurological diseases is an under-investigated area of research." (PMID 28272318, 2017). "Bone marrow-derived mesenchymal stem cells (BMMSCs) may provide a potential cell-based therapy against neurologic disorders through induction of brain-derived neurotrophic factor (BDNF) and vascular endothelial growth factor (VEGF)." (PMID 28492549, 2017). "For these reasons, we believe that prevention and therapy of psychiatric and neurological disorders could be achieved enhancing both BDNF and progranulin levels thanks to drug discovery efforts." (PMID 26869919, 2016). "Dysregulation of the BDNF gene is well documented in neurological disorders." (PMID 26708060, 2016). "BDNF has also received particular interest for its deregulation in nervous system disorders." (PMID 27386199, 2015). "Among the NTs, BDNF has emerged as a major regulator of synaptic plasticity, neuronal survival and differentiation, and also as a potential molecular target for the treatment of neurological disease." (PMID 25954034, 2015). "Notably, edaravone, a free radical scavenger drug currently in clinical trials for various neurological disorders, has been shown to be neuroprotective by enhancing expression of BDNF, Bcl-2 and suppressing caspase-3 activity." (PMID 26016641, 2015). "Furthermore, defective BDNF expression and function is also an important contributor to neurological disease." (PMID 24465693, 2014). "Furthermore, based on some clinical studies about BDNF functions and the effects of acupuncture, we find that acupuncture can also accelerate neural regeneration in patients with some neurological disorder through neurotrophin-mediated effects." (PMID 24566146, 2014). "Thus, modulation of BDNF level in these neurological disorders as a potential therapeutic approach is suggested." (PMID 23320097, 2013). "Brain derived neurotrophic factor has multiple effects in regulating neuronal function and survival, so it is an attractive molecule to target for developing new therapeutic approaches to neurological diseases." (PMID 23320097, 2013).